ARFRP1 (ARF related protein 1)
Description:
Trans-Golgi-associated GTPase that regulates protein sorting. Controls the targeting of ARL1 and its effector to the trans-Golgi. Required for the lipidation of chylomicrons in the intestine and required for VLDL lipidation in the liver.
Synonyms: ARP; ARP1; ARL18
Tractability: PROTAC: ubiquitination databases record sites on it; its protein half-life has been measured.
Gene: Protein-coding gene on chromosome 20 (63,698,622 to 63,708,662, reverse strand). Ensembl gene ENSG00000101246.
Subcellular location: Golgi apparatus; Golgi apparatus, trans-Golgi network
Subcellular location (Human Protein Atlas): Golgi apparatus
Pathways (Reactome):
Vesicle-mediated transport: Retrograde transport at the Trans-Golgi-Network
Gene Ontology:
Molecular function: protein binding; GTPase activity; GTP binding
Biological process: Golgi to plasma membrane protein transport; protein localization to Golgi apparatus; retrograde transport, endosome to Golgi; intracellular protein transport; signal transduction
Cellular component: Golgi apparatus; trans-Golgi network; cytosol; membrane; trans-Golgi network membrane
Genetic constraint (gnomAD): Loss-of-function variants: 19 observed, 29.82 expected, observed/expected ratio (o/e) 0.64, 90% interval 0.44 to 0.94. The upper end of that interval is the gene's LOEUF score, 0.94, which puts it in group 3 of 6, group 1 being the genes least tolerant of losing a copy. Missense variants: 245 observed, 269.11 expected, observed/expected ratio (o/e) 0.91, 90% interval 0.82 to 1.01. Synonymous variants: 133 observed, 115.99 expected, observed/expected ratio (o/e) 1.15, 90% interval 1 to 1.32.
Homologues: Orthologues: chimpanzee ARFRP1 (99% identical), dog ARFRP1 (97% identical), mouse Arfrp1 (97% identical), pig ARFRP1 (97% identical), guinea pig ARFRP1 (96% identical), macaque ARFRP1 (89% identical), zebrafish arfrp1 (77% identical), Drosophila melanogaster Arfrp1 (63% identical), rat Arfrp1 (63% identical), tropical clawed frog arfrp1 (59% identical), Caenorhabditis elegans Y54E10BR.2 (37% identical). Paralogues in human: ARL3 (34% identical), ARL5A (31% identical), ARL5B (30% identical), ARL13B (29% identical), ARL14 (29% identical), ARL2 (29% identical), ARL4A (29% identical), ARL4C (29% identical), ARL1 (28% identical), ARL11 (28% identical), ARL8B (28% identical), ARL8A (27% identical), and 18 more.
Diseases named in the same sentence as ARFRP1 in open-access papers:
ARFRP1 is named in the same sentence as 6 diseases in open-access papers, as found by Europe PMC text mining. Sharing a sentence is not in itself a finding about the gene and the disease. The quoted sentences say what the papers report.
hepatoma (1 paper, 2016). "We showed that protein expression levels of ARFRP1 were higher in hepatoma cell lines than normal liver cells." (PMID 27550144, 2016).
viral infections (1 paper, 2022). "Additional host factors that were significantly enriched include those described for other viral infections, such as negative-stranded RNA virus vesicular stomatitis virus (VSV) (ARFRP1, SYS1, and YKT6) and the human immunodeficiency virus (HIV) (SRP14, DYRK1A, and IL2RA) (33, –, 37)." (PMID 35502904, 2022).
cancer (3 papers, 2015 to 2023). A tumor composed of atypical neoplastic, often pleomorphic cells that invade other tissues. "SRC has been reported to play a role in cancer progression, whereas for ARFRP1, no functional evidence has been presented yet." (PMID 37666855, 2023).
Tumor (2 papers, 2020 to 2023). "For example, we found predictive value of chr20q amplifications in CMS2 tumours treated with FOLFIRI plus cetuximab, which is evident by the significant interactions of TOP1 (pint = 0.07, FDRint < 0.2) and ARFRP1 (pint = 0.01, FDRint < 0.2)." (PMID 37666855, 2023). "We observed amplifications in chromosome arm 20q (chr20q) in 74/373 tumours (19.8%), which includes SRC, TOP1, BCL2L1, ZNF217, AURKA, GNAS and ARFRP1." (PMID 37666855, 2023).
ARFRP1 also shares sentences with these, for which no sentence is quoted: infection (1 paper); Obesity (1).